EGFR (epidermal growth factor receptor)
Diseases named in the same sentence as EGFR in open-access papers (continued):
Sharing a sentence is not in itself a finding about the gene and the disease.
lung cancer (continued). "Lung cancer genetic mutation screening for known oncogenes—epidermal growth factor receptor (EGFR) mutation and anaplastic lymphoma kinase (ALK) rearrangements—were ordered to evaluate whether the tumor could be treated with tyrosine kinase inhibitors, such as erlotinib and crizotinib." (PMID 26425638, 2015). "Though activating mutations in epidermal growth factor receptor (EGFR) resultes in activate transcription of IL-6, and activated Ras may also lead to IL-6 induction in lung cancer cells, the comprehensive mechanisms for IL-6 production in lung cancer cells remain unclear." (PMID 25504436, 2015). "Indeed, the response rate of lung cancer patients with EGFR mutations to EGFR tyrosine kinase inhibitors ranged between 56% and 86% in different clinical trials, thus suggesting that primary resistance is a phenomenon common to different tumors with driver mutations." (PMID 25884512, 2015). "Lung cancer EGFR mutations tend to occur in the kinase domain, whereas GBM EGFR mutations are mainly in the extracellular domain, which could allow the GBM mutant receptors sufficient flexibility within the kinase domain to accommodate lapatinib and other type II EGFR kinase inhibitors." (PMID 25688333, 2015). "However, these unique characteristics of ROR1 have not been reported in ovarian cancer, and may be specific in each cell type, as has been reported for ROR1 and EGFR association in lung cancer models." (PMID 26515598, 2015). "Oncogenic alterations in EGFR are frequently reported in patients with lung cancer and are implicated in the pathogenesis of the disease such as increased tumor proliferation, poor differentiation, and a worse prognosis, indicating that EGFR is an important therapeutic target in lung cancer." (PMID 24658031, 2014). "Interestingly, mutations of the EGF receptor (EGFR) have been associated with several types of cancers, including lung cancer, and targeted therapy using small molecules disrupting kinase activity of EGFR results in considerable clinical benefit in lung cancer patients." (PMID 25030093, 2014). "However, the therapeutic effects of EGFR-TKIs on lung cancers with different EGFR mutation subtypes remain unclear." (PMID 25404271, 2014). "Indeed, some reports in lung cancer have demonstrated discordant mutation patterns between primary and metastatic tumors and a heterogeneous distribution of epidermal growth factor receptor (EGFR) mutations in individual tumors." (PMID 24936796, 2014). "The most frequently occurring secondary EGFR mutation in lung cancer is an exchange of a threonine for a methionine in position 790 (T790M) in exon 20; it is present in about 50 % of all cancers with acquired resistance to EGFR-TKIs but very rare in untreated NSCLC." (PMID 24643470, 2014). "Also, epidermal growth factor receptor-tyrosine kinase inhibitor (EGFR-TKI) therapy for primary lung cancer with EGFR mutation was more common in females, with 6 of 16 female patients (37%) receiving an EGFR-TKI in the course of treatment, in contrast to only 2 of 66 male patients (3%)." (PMID 24957478, 2014). "However, contrary to expectations, the therapeutic efficacy of gefitinib was observed at a very low frequency in all patients with lung cancer, and the improved survival benefit of gefitinib treatment was mostly detected in the specifically selected patients with lung cancer who have EGFR mutations." (PMID 24658031, 2014). "Taken together, our current data and these previous studies indicate that DDX3X is a critical component of the Wnt/β-catenin signaling pathway and that signal switching from EGFR addiction to β-catenin signaling could be induced by DDX3X in lung cancer cells harboring EGFR-activating mutations." (PMID 25343452, 2014). "Furthermore, miRNAs are also associated with the regulation of EGFR in lung cancer." (PMID 23407898, 2013).
lung cancer (continued). "If cytological specimens such as bronchial wash specimens could replace lung biopsy specimens when analyzing EGFR mutation status in patients with inoperable lung cancer, it would be a powerful option, as repeated lung biopsy could be avoided in patients with poor clinical condition." (PMID 23691506, 2013). "Somatic mutations in the EGFR proto-oncogene occur in ~15% of human lung adenocarcinomas and the importance of EGFR mutations for the initiation and maintenance of lung cancer is well established from mouse models and cancer therapy trials in human lung cancer patients." (PMID 24255704, 2013). "Therefore, it has been proposed that genetic alterations in the EGFR gene may be associated with the development and metastasis of lung cancers." (PMID 24137392, 2013). "It remains to be further studied how ERCC1 could affect mutations of the EGFR gene in lung cancer." (PMID 23940741, 2013). "Additionally, most ALK-positive lung cancer is mutually exclusive to EGFR and KRAS mutations." (PMID 23936355, 2013). "While EGFR inhibitors are generally thought to be efficacious primarily in lung cancers expressing EGFR with activating mutations, a substantial number of patients who are negative for these mutations derive some modest benefit from treatment, suggesting that WT EGFR can support tumor growth." (PMID 24349229, 2013). "In summary, by profiling EGFR phosphorylation in wild-type and mutant lung cancer cells, we identified a relationship between EGFR mutations and the phosphorylation of EGFR-Thr654 and -Ser1046, which was associated with AURKA expression in lung cancer patients and may be elicited by AURKA." (PMID 23520446, 2013). "Therefore, together, the evidence from the present and previous studies suggests that EGFR mutations/variants may be involved in the process of the pleural metastasis of lung cancer, although with certain inconsistencies between various studies." (PMID 24137392, 2013). "In addition to oncogenic Ras mutations, 15–30% of samples of NSCLC, which make up 85% of total lung cancers, were also found positive for overexpression of EGFR, which signals via Ras, and has been implicated in their increased ability to invade and metastasize." (PMID 22438909, 2012). "Therefore, molecular tests are routinely performed to identify mutations in oncogenes in lung cancer, including EGFR and ALK; to identify those patients with a high likelihood of response to targeted therapy; and reduce unnecessary side effects of ineffective treatments." (PMID 23198868, 2012). "LUX-lung 3, the largest prospective trial in EGFR mutation positive lung cancer using pemetrexed/cisplatin as a comparison, indicating that afatinib might be a potent first-line treatment in EGFR positive patients due to the improved PFS (11.1 months vs. 6.9 months)." (PMID 23109866, 2012). "Interestingly, EGFR mutations are some of the most common mutations found in lung cancer patients." (PMID 22778711, 2012). "In lung cancer patients, response rates of 72% could thus be demonstrated in the presence of the predictive exon 19 deletions or L858R mutations as compared to 10% in patients with wild-type EGFR." (PMID 22091418, 2011). "Recapitulation of EGFR mutations in lung cancer cells in vitro have demonstrated that it is an example of an 'oncogenic addiction' mutation which provides a biologic explanation for the improved outcome seen in this EGFR mutant NSCLC group relative to the wild type group." (PMID 20942962, 2010). "An individual mosaic for an EGFR mutation may be at increased risk for lung cancer." (PMID 19789704, 2009). "Similarly, EGFR-T790M mutant could cause resistance to Gefitinib and Erlotinib drugs in the treatment of lung cancer." (PMID 19714203, 2009).
lung cancer (continued). "If a certain critical level of EGFR is required to drive the cell toward a malignant phenotype, another mechanism including activating mutations of EGFR and/or the autonomous activation of downstream signalling may be required for the development of lung cancer among Asians." (PMID 18985035, 2008). "The EGFR T790M mutation confers acquired resistance to kinase inhibitors in human EGFR mutant lung adenocarcinoma, is occasionally detected before treatment, and may confer genetic susceptibility to lung cancer." (PMID 17726540, 2007). "Although the functional effects of these polymorphisms have not yet been fully elucidated, we hypothesized that some of these variants may have an effect on EGFR expression or activity, and therefore may play a role in modulating the susceptibility to lung cancer." (PMID 17956637, 2007). "Thus, it is likely that other factors in lung cancer cells may sensitize cells to gefitinib in addition to EGFR gene mutation and the amplification detected by FISH." (PMID 17150102, 2006). "Mutations in several oncogenes are well-characterized driver events in various cancers, e.g., mutations in KRAS G12 residue in pancreatic and lung cancer, BRAF V600 in melanoma, and the EGFR L858 in lung cancer." (PMID 41567248, 2026). "Given the role of EGFR as akey oncogenic driver in numerous cancers, including nonsmall celllung cancer tumors, novel inhibitors to target both resistance mutantand activating mutant tumors are needed." (PMID 41432179, 2026). "Here, we present the case of a 42-year-old Chilean patient with EGFR-mutant lung cancer and leptomeningeal metastasis." (PMID 42222409, 2026). "Inhibitors of epidermalgrowth factor receptor (EGFR)kinase activityare clinically effective treatments for lung cancers driven by activatingmutations in EGFR." (PMID 41432179, 2026). "Despite the initial efficacy of TKIs, the constitutive activation of EGFR and its downstream signaling cascades can attenuate therapeutic sensitivity in lung cancer 30,31." (PMID 41522352, 2026). "Clinical studies have proven the efficiency of EGFR-TKIs in patients with lung cancer bone metastases." (PMID 41551443, 2026). "A patient with EGFR‐mutant lung cancer developed leptomeningeal carcinomatosis years after osimertinib‐induced ILD." (PMID 41537168, 2026). "Another particularly pressing clinical challenge is the high incidence of brain metastases in EGFR-mutant lung cancer patients, which remains difficult to manage effectively." (PMID 41539998, 2026). "While somatic EGFR variants in glioblastomas rarely affect the kinase domain, two of the three GVs in EGFR identified in the germline of glioma patients here and GVs in families with lung cancer affect the intracellular domain of EGFR." (PMID 41546701, 2026). "Afatinib, a second-generation EGFR tyrosine kinase inhibitor, effectively suppresses primary tumor growth and extends progression-free survival in the patient with multifocal lung cancer and glioma driven by EGFR R252C." (PMID 41565660, 2026). "In the context of lung cancer, organoids derived from pleural effusions have been employed to study acquired resistance to epidermal growth factor receptor (EGFR) tyrosine kinase inhibitors and immunotherapy." (PMID 41869438, 2026). "This discovery unveils a potential avenue to overcome immunotherapy resistance in EGFR-driven tumors, particularly lung cancer, through SHP2-targeted combination strategies." (PMID 41538362, 2026). "EGFR mutations remain a major challenge in immunotherapy for non‐small cell lung cancer (NSCLC), with poor responses to immune checkpoint inhibitors driven by mechanisms associated with EGFR mutation‐mediated tumor microenvironment (TME) modulation." (PMID 41144813, 2026). "The third-generation EGFR tyrosine kinase inhibitor (TKI) osimertinib (AZD9291) has significantly improved the survival in EGFR-mutant lung cancer patients." (PMID 42039707, 2026).
lung cancer (continued). "For instance, epigenomic modulators can re-sensitize residual cancer cells to targeted therapies in preclinical models of EGFR-mutant lung cancer." (PMID 42001483, 2026). "PubMed, Web of Science and Embase were searched up to November 2025 for studies reporting histological transformation in EGFR-mutant lung cancer following EGFR-TKI resistance." (PMID 42163145, 2026). "Non‐invasive biomarkers are needed to further personalize EGFR tyrosine kinase inhibitor (EGFR TKI) osimertinib treatment in non‐small cell lung cancer (NSCLC) patients." (PMID 41581122, 2026). "Epidermal growth factor receptor tyrosine kinase inhibitors (EGFR-TKIs) are widely used in the treatment of non–small cell lung cancer due to their precision, efficiency, and ease of use." (PMID 41570298, 2026). "In lung cancer, high AURK expression predicts poor prognosis, and can enhance activation of EGFR/RAS effectors including AKT, ERK1/2, and EMT-associated proteins, promoting drug resistance and tumor invasion." (PMID 41526435, 2026). "A classic targeted sequencing screening panel for lung cancer only sequences the EGFR exons 18–21 that constitute the kinase domain." (PMID 41567248, 2026). "Due to the heterogeneity of lung cancer and according to the nature of progression after EGFR‐TKI resistance, it is divided into three clinical modes: dramatic, gradual, and local progressions." (PMID 40396214, 2025). "Here it is shown that EGFR dictates tumorigenic agrin expression in lung cancer cell lines, genetically engineered EGFR‐driven mouse models, and human specimens." (PMID 40165020, 2025). "Treatments are mostly available for the metastatic stage, but we will also discuss adjuvant therapy for EGFR mutations and ALK fusions, as well as stage III post-chemoradiotherapy treatment for EGFR lung cancer." (PMID 40136350, 2025). "Identification of EGFR as a viable therapeutic target fundamentally transformed the lung cancer treatment landscape." (PMID 41373672, 2025). "In lung cancer, through a comparison of RNA networks in EGFR wild‐type and mutant non‐small cell lung cancer, it was correlated with shorter survival." (PMID 41225782, 2025). "The role of EGFR in cancer progression and as a therapeutic target in various human malignancies, including cholangiocarcinoma, lung cancer, colon cancer, and breast cancer, has been well-established." (PMID 40148311, 2025). "A combination assay of melittin peptides with gefitinib, a chemotherapeutic drug that can inhibit EGFR, was then assumed to have synergistic effects against lung cancer cells." (PMID 40141140, 2025). "Altogether, these results strongly suggest that LMK235 amplifies osimertinib-induced apoptosis, highlighting the co-treatment as a promising strategy to overcome osimertinib resistance in EGFR-mutant lung cancer cells." (PMID 40290805, 2025). "In the current study, we aimed to investigate the outcomes of lung cancer patients concomitantly using EGFR TKIs and analgesics in a real‐world setting." (PMID 40650440, 2025). "PM2.5 can increase oxidative stress and inflammation, induce genetic alterations and activation of oncogenes (including the epidermal growth factor receptor, EGFR), and contribute to lung cancer progression." (PMID 39578555, 2025). "The EGFR, highly expressed on numerous tumor cells including squamous cell carcinoma, breast cancer, and lung cancer, has been extensively studied and clinically exploited." (PMID 41216197, 2025). "DNA-based assays, including targeted gene panels and sequencing technologies, have enabled biomarker-driven therapies in many malignancies such as lung cancer (EGFR inhibitors) and melanoma (BRAF inhibitors)." (PMID 41228245, 2025). "Lung cancer development involves mechanisms like reduced EGFR/EGF ubiquitination driving cancer cell behaviors and immune evasion via loss of PD‐1/PD‐L1 ubiquitination." (PMID 40313038, 2025).
lung cancer (continued). "In other cancers, such as lung cancer, miR-218-5p was found to directly bind to the 3′ region of EGFR gene, inhibiting their effect on cell growth and angiogenesis." (PMID 40805149, 2025). "Human H292 lung cancer cells with CMTM4 KO showed significant decreased EGFR surface expression detected by flow cytometry." (PMID 39948411, 2025). "This “gene-editing-free” precise immune activation model not only provides a new treatment option for refractory lung cancers such as EGFR-TKI-resistant cases but also expands the application boundaries of solid tumor immunotherapy." (PMID 40959071, 2025). "In conclusion, this study highlights the significant influence of EGFR activation on EV secretion and cargo composition while demonstrating that EGFR inhibition via gefitinib alters EV-mediated signaling in lung cancer cells." (PMID 40210802, 2025). "In this regard, osimertinib, a third-generation EGFR TKI, has greatly improved the outcome for patients with EGFR-mutated lung cancer." (PMID 40243603, 2025). "Younger patients with lung cancer also have distinct immune profiles and tumor mutational burden (TMB), related to the high prevalence of targetable driver alterations (e.g., EGFR mutations and oncogene fusions)." (PMID 40641929, 2025). "CAFs significantly contribute to lung cancer resistance to EGFR-TKIs by inducing EMT through specific CAF-mediated signaling pathways." (PMID 40002883, 2025). "In this review, we discuss the role of mutant EGFR in regulating lung cancer growth and cellular metabolism." (PMID 40940888, 2025). "Of note, AREG, EREG, FOSL1, MYC, and PLAU are involved in the EGFR signaling pathway, which is a key pathway in lung cancer development." (PMID 39858622, 2025). "The same analysis reported the common features of the associated lung cancer, including the adenocarcinoma pathology and at least one driver mutation in nearly half of the cases, including KRAS, EGFR, ALK, BRAF, and ATM." (PMID 41476748, 2025). "Toward this, first, we acquired a dataset that contains pre-treatment tumor RNA-seq samples from 8 patients with EGFR-mutant lung cancer treated with the tyrosine kinase inhibitor, Osimertinib30." (PMID 40463038, 2025). "This suggests that the anticancer activity of EGCG in H1299 and A549 lung cancer cells is, at least in part, mediated through the inhibition of the EGFR/PI3K/Akt axis." (PMID 40161336, 2025). "The cumulative effects of PM2.5 exposure, including ROS generation, inflammation, DNA damage, and activation of oncogenic pathways like EGFR and AhR, create a vicious cycle that promotes lung cancer development and progression." (PMID 39578555, 2025). "Examples include prostate cancer and EGFR-mutant lung cancer, in which adenocarcinomas transdifferentiate into neuroendocrine cancers under select pressure of targeted therapy." (PMID 40553565, 2025). "To demonstrate the utility of ChatChemTS, we performed de novo designs of a chromophore and an epidermal growth factor receptor (EGFR) inhibitor, the latter of which is a common treatment for breast and lung cancers." (PMID 40128788, 2025). "Quercetin has been shown to dramatically suppress the expression of growth factor signaling molecules, including EGFR, pAKT, pGSK-3β, β-Catenin, NFκB, and cyclin D, in lung cancer cells (A549)." (PMID 40728967, 2025). "Targeted therapy for EGFR and ALK mutations in lung cancer is one of the most successful applications of multi-omics strategies in cancer treatment." (PMID 41269529, 2025). "The epidermal growth factor receptor (EGFR) pathway is a well-known driver of lung cancer progression, particularly in NSCLC9,10." (PMID 41254241, 2025). "Despite advancements in treatments for metastatic non‐small cell lung cancer (NSCLC), patients harboring sensitizing epidermal growth factor receptor (EGFR) mutations ultimately experience treatment failure with frontline tyrosine kinase inhibitors (TKIs)." (PMID 40289745, 2025).